APOB (apolipoprotein B)
Diseases named in the same sentence as APOB in open-access papers (continued):
Sharing a sentence is not in itself a finding about the gene and the disease.
diabetes (continued). "In conclusion, ApoA1/HDL-C was highly associated with diabetes and was superior to ApoB/LDL-C, ApoA1, ApoB, LDL-C/HDL-C, ApoB/ApoA1, LDL-C, HDL-C, and TG among the general Taiwanese population." (PMID 24093822, 2013). "These associations are expected and underline the known relation of LDL(−) and oxLDL with the presence of diabetes and hypertriglyceridemia, and of apoB and glLDL with hypertriglyceridemia." (PMID 23915379, 2013). "For univariate analysis in this study, ApoA1/ HDL, ApoB/LDL, ApoB/ApoA1, and LDL/HDL were separately and significantly associated with diabetes." (PMID 24093822, 2013). "This study reported that apolipoproetein B (apoB), apoA-I, apoB/apoA-I, alcohol intake, log-transformed TG, log-transformed hsCRP, LDL-cholesterol, hypertension, diabetes, regular exercise, and BMI were significantly associated with the FRS." (PMID 23028747, 2012). "The specific protein of apolipoprotein B (ApoB) on LDL is glycated in diabetes, and this leads to rapid scavenger uptake of the LDL, which gives rise to foam cell formation in atherogenesis." (PMID 22110482, 2012). "Overall, low income level, history of hypertension, history of diabetes, and ApoB/ApoA1 ratio were more frequent in cases than in controls (P < 0.05 for all comparisons)." (PMID 22245707, 2012). "Increased UAE was found to be associated with ApoB-containing lipoproteins in patients with diabetes and the phenotype of hypertriglycerides/hyper-ApoB." (PMID 22958709, 2012). "An apoB level <80 mg/dL was suggested for patients with the highest CVD risk, i.e. known CVD or diabetes plus ≥1 additional major CVD risk factor." (PMID 21356116, 2011). "SM levels were significantly correlated with fibrinogen levels, diabetes, apoB, and triglyceride levels." (PMID 21521522, 2011). "The final logistic model for presence of obesity included age, sex, diastolic blood pressure, diabetes, homocysteine, insulin resistance, apoA1, and apoB." (PMID 21159217, 2011). "In conclusion, after accounting for classic risk factors, our study identified adiponectin, apoB, CRP, IL-1ra and ferritin as the strongest predictors of incident diabetes." (PMID 20396381, 2010). "Independent risk factors at age 50 for death due to acute MI before the 70-year examination were high BMI, high DBP, high ApoB/ApoA1 ratio, T wave abnormalities, smoking and diabetes mellitus." (PMID 16519804, 2006). "Significant differences were observed between the simple heart failure (SHF) group and the CRS group in terms of age, history of diabetes mellitus, levels of triglycerides (TG), apolipoprotein A1 (apo-A1), apolipoprotein B (apo-B), ApoB/ApoA1 ratio, and serum creatinine (Scr)." (PMID 41908053, 2026). "Although carriers of LoF APOB variants exhibited a substantially reduced risk of atherosclerotic events, this benefit was outweighed by a significant long‐term increase in the risk of CLD, amplified in individuals with obesity or diabetes." (PMID 41549954, 2026). "This study demonstrates, for the first time, that circulating Lp(a) is associated with arterial O2.− production independently from ApoB and other cardiovascular disease risk factors, primarily in individuals without diabetes." (PMID 41164877, 2026). "Adjustment for the apoB/apoA-1 ratio did not affect this association among those with diabetes and only slightly attenuated the association for those with IFG and high glucose." (PMID 39915078, 2025). "This study aimed to investigate the association between ApoB levels and glycemic parameters, including fasting glucose, insulin resistance, and glycated hemoglobin (HbA1c), in individuals without diagnosed diabetes." (PMID 40423035, 2025). "Spearman correlation analysis revealed that positive associations between CHD inwomen and multiple factors, including lifestyle factors (smoking and alcoholconsumption), clinical conditions (hypertension and type 2 diabetes mellitus),and biochemical markers (BMI, TC, ApoB, Lp(a), WBC, NE, and PLT)." (PMID 40776945, 2025).
diabetes (continued). "Personalized therapeutic strategies that incorporate ApoB levels, metabolic phenotypes, and advanced lipoprotein profiling offer significant potential to optimize treatment, particularly in complex populations such as individuals with type 2 diabetes mellitus." (PMID 41346943, 2025). "In this research endeavor, we hypothesized that ApoB may influence renal function in individuals with diabetes." (PMID 40379620, 2025). "The search was carried out on Medline using the keywords non-HDL-C, apolipoprotein B, cardiovascular prevention, risk stratification, diabetes, obesity, and hypertriglyceremia in combination with the Boolean operators AND or OR." (PMID 40710781, 2025). "FSG: fasting serum glucose; HOMA-IR: hemostasis model assessment of insulin resistance; LDL/HDL-C: high-density lipoprotein cholesterol/low-density lipoprotein cholesterol ratio; ApoB/ApoA: apolipoprotein A/apolipoprotein B ratio; BMI: body mass index; DM: diabetes mellitus." (PMID 39081429, 2024). "It should be mentioned that according to clinical guidelines, a large number of the patients with diabetes were probably treated with statins, which may raise apolipoprotein A1 and lower apolipoprotein B." (PMID 38084202, 2023). "In addition, a positive relationship was identified between fish oil use and the serum levels of TC, LDL-C, HDL-C, and ApoB (all p < 0.05) among participants with prediabetes or diabetes." (PMID 37513593, 2023). "These modifiable risk factors include hypertension, diabetes, smoking, abdominal obesity, psychological index, lack of exercise, lack of fruits and vegetables, apolipoprotein B/apolipoprotein A1 (ApoB/ApoA1) ratio, and the use of alcohol." (PMID 35812625, 2022). "We can hypothesize that female, waist circumference ≥ 90 cm, diabetes, FG ≥ 88 mg/dL, triglyceride ≥ 160 mg/dL, HDL-C ≤ 0.8 mmol/L, LDL-C ≥ 2.0 mmol/L and apolipoprotein B ≥ 0.70 g/L may be the risk factors of obesity in patients with schizophrenia." (PMID 35690794, 2022). "Female, waist circumference ≥ 90 cm, diabetes, FG ≥ 88 mg/dL, triglyceride ≥ 160 mg/dL, HDL-C ≤ 0.8 mmol/L, LDL-C ≥ 2.0 mmol/L and apolipoprotein B ≥ 0.70 g/L may be the risk factors of obesity." (PMID 35690794, 2022). "Additionally, it has been shown that the anti-inflammatory functionality of apoB-depleted plasma was strongly impaired in type 2 diabetes mellitus." (PMID 35413066, 2022). "Previous studies have shown that the most serious risk factors for PAD were diabetes and smoking; others included advanced age, hypertension, and hyperlipidemia; potential risk factors included CRP, fibrinogen, homocysteine, apolipoprotein B, lipoprotein (a), and elevated plasma viscosity." (PMID 36514151, 2022). "The higher ApoB/ApoA1 ratio seen in our study of patients in late CKD compared to early CKD, is relevant given the magnified cardiovascular risk associated with progressive diabetes-associated CKD." (PMID 35295919, 2022). "Furthermore, in patients with diabetes significantly higher levels of oxidized LDL (Ox-LDL) in relation to apoB concentration (Ox-LDL/apoB ratio) were attributable to the -108 TT genotype associated with lower PON1 in comparison with the CT or CC genotypes." (PMID 33670025, 2021). "In the Logistic regression analysis, diabetes, LDL-C and Lp(a) are risk factors of CAHD in all patients, while in High-LDL-C Group, they were age, LDL-C, non-HDL-C and ApoB, in Low-LDL-C Group, they were age, Lp(a) and ApoB." (PMID 33468066, 2021). "The known risk factors (such as diabetes, hypertension, dietary factors, obesity) and lipoprotein-associated risk (low HDL-C levels, higher TGs, and elevated apolipoprotein B levels) could explain premature CAD among South Asians." (PMID 34957228, 2021). "Factors include the following: the presence of hypertension, an increased apolipoprotein B (Apo B) to Apo-A1 ratio, diet, psychological stress, smoking, high alcohol consumption, diabetes, chronic kidney disease, and cardiac conditions like atrial fibrillation." (PMID 34177775, 2021).
diabetes (continued). "In a univariate binary logistic regression analysis, female, NIHSS, diabetes mellitus, and FIB were risk factors of vitamin D deficiency in all patients (OR = 1.066 ∼ 1.584, P ≤ 0.001), while the ApoA-I, ApoA-I/ApoB and HDL were protective factors (OR = 0.331 ∼ 0.569, P < 0.001)." (PMID 33536895, 2020). "Furthermore, we also showed that the Lp-PLA2 concentration was definitely correlated with apoB and apoB/apoA1 after adjustment for hypertension, age, gender, smoking, and diabetes mellitus." (PMID 33029257, 2020). "After adjustment for several risk factors regarding CAD, like hypertension, gender, smoking, age, and diabetes mellitus, there had still been positive associations between the Lp-PLA2 concentration and apoB (β = 0.364, P < 0.001), as well as apoB/apoA1 (β = 0.390, P < 0.001)." (PMID 33029257, 2020). "Fasting and postprandial apolipoprotein B48, the main protein in chylomicrons, and its remnants have been associated with SA in many studies in populations both with diabetes and without." (PMID 32244483, 2020). "Moreover, when models were concurrently adjusted for gender, age, apoB concentration, diabetes, past CVD history, CRP concentration, and eGFR; again significant interaction with UAE was demonstrated only for apoA-I/HDL-C." (PMID 30813431, 2019). "With adjustment of ANOVA models for gender and age and further adjustment for gender, age, apoB, diabetes, past CVD history, and eGFR, all NMR lipoprotein markers remained significantly associated with the UAE groups except for medium and small HDL-P and the ratio of apoA-I/HDL-P." (PMID 30813431, 2019). "With adjustment of ANOVA models for gender and age and further adjustment for gender, age, apoB, diabetes, past CVD history, and eGFR; all lipid and lipoprotein markers remained significantly associated with the UAE groups except for apoA-I, cholesterol, and LDL-C." (PMID 30813431, 2019). "Similarly, small proportions of GRS50 were mediated: 8.1% (95% CI: 5.5–11.8%) by apoB, 1.2% (95% CI: 0.5–3.0%) by apoA‐I, 4.2% (95% CI: 1.3–7.5%) by blood pressure, and −0.9% (95% CI: −3.7% to 1.6%) by diabetes mellitus." (PMID 28320750, 2017). "Subjects with pre-diabetes had higher ApoB/ApoA-I ratios than those with NGT." (PMID 28110289, 2017). "In the current cross-sectional study, we observed strong positive associations between the ApoB/ApoA-I ratio and the risk of pre-diabetes and diabetes in women, independent of traditional metabolic risk factors." (PMID 28110289, 2017). "The increase in the number of atherogenic particles reflected by high apolipoprotein B (apoB) concentrations may contribute to an increased cardiovascular disease (CVD) mortality in people with diabetes (phenotype B)." (PMID 29225514, 2017). "A trend toward significance between worse kidney function and apoB was shown in diabetes patients without CVD, however, this association weakened after further adjustment." (PMID 28957410, 2017). "In conclusion, our findings indicate positive associations between the ApoB/ApoA-I ratio and the risk of pre-diabetes and diabetes in Chinese women, independent of traditional metabolic risk factors." (PMID 28110289, 2017). "Insulin sensitivity in clamp studies was independently associated with serum bicarbonate and apolipoprotein A1: apolipoprotein B ratio in a sample of CKD patients without diabetes." (PMID 27716263, 2016). "When entering major risk factors in Cox regression analyses, vitamin D levels were negatively related to all-cause mortality in men with diabetes, independently of baseline age, PTH, HbA1c, waist circumference, mean 24 h systolic ambulatory blood pressure and apoB levels." (PMID 26078787, 2015).
diabetes (continued). "Among diabetes, hypertension, obesity and smoking, a family lipoprotein disorder such as a high level of serum apolipoprotein B (Apo B) or/and a lower level of serum apolipoprotein A-1 accounted for almost all the population attributable risk of ACS, according to the Framingham study." (PMID 26103962, 2015). "The top tertile of ApoB/LDL-C was significantly associated with diabetes at an OR of 2.03 (P-trend = 0.028) in women, but not in men." (PMID 24093822, 2013). "During 2005–2008, unadjusted concentrations of apolipoprotein B ≥80 mg/dl were observed in 72.8% of participants with diagnosed diabetes, 87.9% of participants with undiagnosed diabetes, 86.6% of participants with prediabetes, and 77.2% of participants with normoglycemia." (PMID 23360385, 2013). "The objective of this study was to examine changes in concentrations of lipids and apolipoprotein B among participants stratified by glycemic status (diabetes, undiagnosed diabetes, prediabetes, and normoglycemia) in the United States from 1988–1991 to 2005–2008." (PMID 23360385, 2013). "Only the top ApoB/LDL tertile independently of other confounders conferred risk for diabetes at approximately 2-fold ORs in women but not in men." (PMID 24093822, 2013). "Consequently, the objective of the present study was to examine changes in concentrations of lipids with a focus on apolipoprotein B among adults with diagnosed and undiagnosed diabetes from 1988–1991 to 2005–2008." (PMID 23360385, 2013). "The heparin sulphate proteoglycans that bind apo B lipoproteins may have greater affinity for TRL remnants because of cooperative apolipoprotein binding domains principally between apo B and apo E and exacerbates as a consequence of diabetes." (PMID 21961070, 2012). "Somewhat surprisingly, one of the strongest predictors of diabetes was apoB." (PMID 20396381, 2010). "Notably, in our cohort, the risk of CLD remained high in carriers without diabetes, suggesting that diabetes acts as an amplifier of CLD risk in APOB carriers." (PMID 41549954, 2026). "Additionally, Shapley Additive Explanation (SHAP) analysis indicated that age, BMI, TC, ApoB, TG, hypertension, TP, HDL-C, and WBC may serve as risk factors for pre-diabetes." (PMID 40140819, 2025). "The LASSO regression algorithm was used to conduct feature selection from 30 factors, ultimately identifying nine non-zero coefficient features associated with pre-diabetes, including age, TG, TC, BMI, Apolipoprotein B, TP, leukocyte count, HDL-C, and hypertension." (PMID 40140819, 2025). "Additionally, the application of smooth curve fitting will contribute to a more detailed elucidation of the specific relationship between serum TT concentration and serum apoB concentration under different factors (Drinking, Smoke, Diabetes, Hypertension, and High cholesterol level)." (PMID 38435750, 2024). "HOMA-IR: hemostasis model assessment of insulin resistance; LDL/HDL-C: high-density lipoprotein cholesterol/low-density lipoprotein cholesterol ratio; ApoB/ApoA: apolipoprotein A/apolipoprotein B ratio; DM: diabetes mellitus." (PMID 39081429, 2024). "In this study, we examined the correlation between apoB and Klotho while considering a range of potential confounding factors, including gender, age, race, education level, ratio of family income to poverty, hypertension, high cholesterol level, BMI, diabetes, drinking, smoking, and cancer." (PMID 37352065, 2023). "Additionally, patients with stroke recurrence had higher plasma LDL-C levels, higher ApoA-I and ApoB concentrations, higher incidence of hypertension, higher incidence of diabetes mellitus, and poorer medication compliance compared to patients without stroke recurrence." (PMID 38274879, 2023). "Finally, no genetic associations of LDL cholesterol, apoB, TG, alcohol consumption, or diabetes with risk of AD were observed." (PMID 37195665, 2023).
diabetes (continued). "Additionally, the concentration of LDL-C and apolipoprotein B in type 1 diabetes mellitus patients may play a key role in endothelial functional impairment." (PMID 35931987, 2022). "MR-PRESSO detected outliers in the overall associations with diabetes, LDL-cholesterol, HDL-cholesterol, apolipoprotein B and diastolic blood pressure, and sex-specific association with LDL-cholesterol, HDL-cholesterol, and apolipoprotein B, where we used corrected estimates from MR-PRESSO." (PMID 36045366, 2022). "Spearman correlation analysis between their expression and clinical parameters showed that S1PR5 was associated with diabetes, heart rate, TG, TC, LDL-C, ApoB, and fasting blood glucose, while CARNS1 was associated with uric acid, suggesting S1PR5 and CARNS1 may be related to CHD." (PMID 35837598, 2022). "In order to determine if the same relationship observed in cells and mice also existed in humans, we compared the relative reduction in apoB and TG levels in carriers of the rs12740374 variant with diabetes with that in carriers without diabetes in almost 500,000 individuals in the UK Biobank." (PMID 35113816, 2022). "The association between ApoB/ApoA1 ratio and Lipoprotein (Total Cholesterol/HDL-c) ratio, modified Gensini score and Framingham risk score were compared using multivariate linear regression analysis after adjustment for age, sex, BMI, smoking, drinking, hypertension and diabetes." (PMID 31744496, 2019). "Therefore, in this observational study, we aimed to evaluate the associations between the level of ApoB/ApoA-I ratio and the risk of T2DM and pre-diabetes in both Chinese men and women and also investigate the correlations between the ratio and other lipid and glycaemic traits." (PMID 28110289, 2017). "These factors may be responsible for the lack of significant association between the ApoB/ApoA-I ratio and diabetes risk in men." (PMID 28110289, 2017). "The conclusions are as follows: 1) Statistically significant differences were observed among the two groups in terms of gender, hypertension, age, duration of diabetes mellitus, plaque location, TG, TC, Apo A1, VLDL, VLDL/ApoB, HDL/ApoA1 (P<0.05)." (PMID 41403409, 2025). "The primary risk factors for ASCVD include lipoprotein particles containing apolipoprotein B (ApoB), with low-density lipoprotein (LDL) being the most common, along with high blood pressure, smoking, obesity, and diabetes." (PMID 40264814, 2025). "SHAP analysis indicated that age over 53 years, BMI over 25, TC over 5.6 mmol /L (100.8 mg/dl), ApoB value over 0.9 g/L, TG over 1.4 mmol /L (124.2 mg/dl), hypertension, TP over 81 g/L, HDL_C less than 1.2 mmol /L (46.4 mg/dl), WBC over 6.2 × 109 /L may be the risk factors for pre-diabetes." (PMID 40140819, 2025). "The depression group showed significantly higher levels of ApoB, TyG, gTyG, Age, T, CHO, CH50, SG, Cl, TG, A/G, DBIL, RDWSD, FDP, PLT, and HGB and higher prevalence of hypertension, CHD, diabetes, stroke, OP, and anemia (all P < 0.05)." (PMID 41458557, 2025). "Age, sex, hypertension status, diabetes, ALT, FBG, TC, LDL, TC/HDL, ApoB, ApoA1/ApoB, cTnT, Fg, and PCSK6rs1531817 genotypes were the variables tested in the comparison among patients with single vessel disease (SVD), DVD, and TVD." (PMID 39039525, 2024). "After adjusting the confounders including gender, smoking history,diabetes, hypertension, TG, TC, HDL-C, LDL-C and ApoB, the CC genotypeof rs7257062 was identified to be an independent risk factor for CAD (OR= 1.581, 95% CI: 1.094–2.284, p = 0.015)." (PMID 39076552, 2024). "A cheaper alternative would be to measure apolipoprotein B (apoB) levels, which reflect sdLDL-C and score over LDL-C levels in patients with diabetes mellitus." (PMID 36819362, 2023).